IL18 (interleukin 18)
Diseases named in the same sentence as IL18 in open-access papers (continued):
Sharing a sentence is not in itself a finding about the gene and the disease.
tumor (continued). "In the Ctrl group, 18.8% percent of the tumor contained >50 CD8+ cells per microscopic field compared to 6.6%, 2.9% and 0.0% respectively for groups that received neutralizing antibodies to IL-18, IFN-γ, or both." (PMID 21935389, 2011). "Herein, we showed that anti-murine VEGF antibody completely abrogated IL-18 secretion from tumor-activated HSE cells and that RVL abolished IL-18 production from VEGF-activated HSE cells." (PMID 21569399, 2011). "Thus, the addition of IL-18, an immunostimulatory cytokine with an established safety profile, to standard Doxil chemotherapy may significantly increase tumor response and lead to increased tumor elimination." (PMID 20003308, 2009). "IL-18 alone has minimal effect when compared to IL-18 in combination with IL-12, in inducing the Th1 cytokine IFN-γ production by tumor-draining lymph node cells in a murine model." (PMID 23674953, 2005). "Tumor type segregation of correlation analysis showed STS tumor growth correlated significantly with increased serum levels of GM-CSF, IL-2, IL-6, IL-7, IL-18 & MCP-1, whereas increased circulatory CD4+ and CD8+ T cells numbers correlated with STS tumor regression with CPMV treatment." (PMID 40386779, 2025). "IL‐18 colocalized with NFAT1 and p‐p38 in the spinal dorsal horn on day 14 post‐tumor inoculation." (PMID 39957627, 2025). "Except for IL-2, GM-CSF, IL-6, and IL-18 showed a negative correlation with tumor growth in CRT-NP treated patients." (PMID 40386779, 2025). "Elevated levels of IL-18 may indicate a more aggressive disease or worse prognosis in NHL by affecting tumor growth and survival of tumor cells." (PMID 40646161, 2025). "In the total NK cell population, stimulation with IL-12 and IL-18 induced a modest, but non-significant, increase in CD107a expression in the liver compartment compared to the tumor, with a higher expression with K562 target cells." (PMID 41268557, 2025). "This chronic inflammatory state promotes the release of cytokines (e.g., IL-1β, IL-6, IL-10, IL-18, TNF-α) and growth factors that facilitate tumor cell proliferation, invasion, and angiogenesis, while simultaneously impairing effective immune surveillance against malignant cells." (PMID 41114747, 2025). "Collectively, non-B-FLCs drive inflammation and tumor progression by activating inflammasome by enhancing the expression of cleaved caspase-1 and the maturation of IL-1β and IL-18." (PMID 40806736, 2025). "Within the tumor microenvironment (TME), the early stages are characterized by a predominance of M1 macrophages, NK cells, and CD4+/CD8 + T cells, which secrete anti-tumor factors including IL-2, IL-12, IL-18, and IFN-γ." (PMID 41384115, 2025). "Additionally, IL-18, IL-1β, and LDH were released to the extracellular environment, thereby activating anti-tumor immune responses." (PMID 39743555, 2025). "Interestingly, we observed stronger MC38 tumor-protective immune memory with RMP-IL-18mutE4 than RMP-IL-18mutE2, highlighting IL-18’s complex role in systems with variable PD-1 and IL-18R expression on T cells and myeloid subsets." (PMID 41488627, 2025). "Furthermore, tumor-targeted CAR T cells can secrete IL-12 and IL-18 to eliminate ovarian and other tumors effectively." (PMID 40861448, 2025). "Further, serum cytokine levels, such as MCP-1, GM-CSF, IL-2, IL-6, IL-7 and IL-18, correlated with tumor growth independent of various treatments." (PMID 40386779, 2025). "Concentrations of IL‐18 were around 30 times higher in MUE dogs (median 3 pg/mL, range 0.52 pg/mL) compared to IE (median 0.09, range 0.15 pg/mL) and 12 times higher compared to dogs with neoplasia (median 0.25 pg/mL, range 0.15 pg/mL); (p < 0.001)." (PMID 40859633, 2025). "Remarkably, IL-18-secreting CAR-T cells have shown improved anti-tumor activity by stimulating the activation of NK cells and M1-polarized macrophages, which enhance inflammation and promote anti-tumor immune responses." (PMID 39791742, 2025).
tumor (continued). "T cells armored with GzB-IL18 produced significantly more TNF-⍺ than those with pro-IL18 or no armoring when stimulated on tumor cell monolayers or with CD3+CD28 crosslinking." (PMID 38745414, 2024). "WTX-518, an IL-18 pro-drug resistant to IL-18BP inhibition, is conditionally activated within the tumor microenvironment, promotes increased influx and activation of NK cells and polyfunctional CD8 T cells, and induces regressions in mouse tumor models." (PMID 39769266, 2024). "This may be due to the fact that IL-18 induces endothelial adhesion molecules like VCAM and ICAM, which support tumor cell metastasis." (PMID 38391959, 2024). "Furthermore, IL-18-releasing CAR-T cells polarized pro-tumoral macrophages toward an antitumoral phenotype, suggesting potential for modulating the tumor microenvironment." (PMID 39640015, 2024). "In this study, we demonstrated that the infection of B16F10 tumor cells with the rLaSota-BC-RFP virus increased the infiltration of CD8+ and CD4+ T cells in the tumor tissues, accompanied by elevated levels of IL-12, IFN-γ, IL-15, TNF-α, and IL-18." (PMID 39458338, 2024). "Some of the most widely used bacterial vectors are derived from Salmonella typhimurium, which can be modified to secrete LIGHT/TNFSF14, IL18, FASL and TRAIL cytokines, and when injected intravenously into laboratory animals, contribute to the tumor reduction in vivo." (PMID 38715617, 2024). "In fact, the release of the main effectors of pyroptosis (IL‐1β, IL‐18 and HMGB1) breaks down the ‘cold’ tumour properties and increases the infiltration of anti‐tumour immune cells in the TME, while at the same time decreasing the infiltration of suppressor immune cells." (PMID 38652105, 2024). "Nonetheless, we did not detect activation of pro-IL18 following CD3+CD28 crosslinking or tumor cell exposure in any of the CAR T cell populations we studied." (PMID 38745414, 2024). "IL18 armoring systems generally express the active form of this cytokine in conventional (mainly αβ) T cells, leading to enhanced anti-tumor efficacy even without lymphodepletion." (PMID 38745414, 2024). "In our studies, although IL-18 levels were higher in serum and tumor of IMSA101-treated mice, we did not observe differences in IL-18BP levels between cohorts receiving IMSA101 and CART, either alone or in combination." (PMID 38730243, 2024). "PDA7940b tumor-bearing mice were treated with a single i.t. injection of IMSA101 or were left untreated for control, and tumors were harvested at different time points for IL-18 ELISA of tumor cell lysates." (PMID 38730243, 2024). "The anti-tumor effects of mono-treatment with reovirus type 3 Dearing strain (RC402 and RP116) and in combination with interleukin (IL)-18/-21-pretreated eNK cells were investigated on BCC lines (5637, HT-1376, and 253J-BV) using intravesical therapy to simulate in vitro model." (PMID 38548803, 2024). "Mice lacking ASC and caspase-1 showed an increased tumor burden related to attenuated levels of IL-1β and IL-18 in the site of the tumor." (PMID 39684769, 2024). "Treatment with pCAR-H/T + nil CAR T cells resulted in short-lived tumor control followed by relapse and this was not improved by armoring with pro-IL18." (PMID 38745414, 2024). "BPT567 exhibits notable single-agent anti-tumor efficacy, superior to that of anti-PD-1 antibody single-agent or non-targeted IL-18." (PMID 39769266, 2024). "Moreover, IL‐12 and IL‐18 increase the secretion of IFN‐γ in human γδT cells and promote tumor cell apoptosis." (PMID 38604998, 2024). "This group employed IMSA101, a small molecule and an analogue of cGAMP that is an agonist of STING (stimulator of interferon genes) and that induces a pro-inflammatory cytokine milieu in general and IL-18 secretion in particular and thereby enhances CART anti-tumor efficacy." (PMID 39769266, 2024).
tumor (continued). "An anti-tumor role for IL-18 (formerly called IFNγ-inducing factor) was also proposed, based on its capacity to stimulate the production of IFN-γ by activated lymphocytes, subsequently enhancing apoptosis of tumor cells." (PMID 38954024, 2024). "Collectively, these findings may have contributed significantly to the strong armoring effect of IL18 in CAR γδ T cells, favoring tumor eradication in most cases where CAR γδ T cells alone achieved much poorer disease control." (PMID 38745414, 2024). "Mast cell proteases significantly influence not only inflammation but also angiogenesis, thus affecting tumor growth and progression by acting on immunosuppression, release of the proangiogenic cytokines VEGF, IL-18, and TNF-α, mitogenic factors, and extracellular matrix degradation." (PMID 37185713, 2023). "Therefore, mRNA expressions of chemokines CCL2, CCL17 and CCL22, as well as IL-6, IL-18, TNF-α and IFN-γ, in tumor tissues and H22 cells were detected by RT-qPCR." (PMID 36674931, 2023). "However, on the intestinal mucosal surface, the intestinal barrier function and tumor surveillance depend on activation of inflammasome to product active IL1B and IL18." (PMID 36741232, 2023). "Prior to conducting the assay, we identified a subset panel of factors known to mediate the induction of apoptosis in tumor cells: IL-27, IL-1b, IL-2, CXCL10, IL-12p70, G-CSF, IFN-g, TNF-a, IFN-a, CCL2, IL-9, TNF-b, TRAIL, IL-18, IL-21, TSLP." (PMID 37468934, 2023). "Moreover, IL-18 production and administration was shown to limit the migration of colon MC38 tumor cells into the liver by increasing the activation of NK cells and their cytotoxicity through FASL." (PMID 37298187, 2023). "Moreover, IL‐1 and IL‐18 production needed AIM2, which enhanced Treg accumulation and tumor progression in vivo." (PMID 37752941, 2023). "Moreover, tumor growth was observed to be accelerated in NLRP3 knockout mice, concomitant with decreased IL-18 levels in the tissue." (PMID 37497237, 2023). "Notably, the secreted IL-1β/IL-18 activates downstream signaling pathways by binding to their respective receptors (IL1R1, IL-18Rα, and IL-18Rβ) on tumor cells, therapy performing multiple functions in tumor progression." (PMID 36823153, 2023). "There has been significant work in developing a form of IL-18 suitable for clinical application, including the development of a form of IL-18 that does not bind to IL-18DR and therefore elicits greater anti-tumor potency than wild-type IL-1842." (PMID 37914685, 2023). "Furthermore, certain cytokines/chemokines like TNF-α, IL-18, and RANTES are believed to contribute directly to tumor growth by stimulating receptors on tumor cells." (PMID 38247456, 2023). "Our results showed that IL-12, IL-15, and IL-18-activated NK cells had memory-like properties, which resulted in an increased production of IFN-γ and TNF-α upon restimulation with tumor cells and heightened cytotoxicity when compared to IL-15-maintained NK cells." (PMID 36932395, 2023). "Patients with the highest difference in IL18 expression between tumor and nontumor tissues had the poorest prognosis." (PMID 37575948, 2023). "The enzyme‐linked immunosorbent assay (ELISA) analysis of coculture supernatants found that after the knockdown of GSDMB in tumor cells, the addition of IBI315 no longer caused the elevation of IL‐18 in the coculture supernatants." (PMID 37587833, 2023). "In addition, IL-17A can promote the secretion of inflammatory factors such as IL-1β、IL-18 and immune antigens, and recruit CD8 + T cells to infiltrate tumours." (PMID 37211606, 2023). "Activating TLR4 may recede the suppressive inflammatory factors expression, including NF-κB, IL-1β, and IL-18 by the ASCL2 regulation, and induce the inflammatory injury to tumor cells, thereby being involved in the prognosis of this disease." (PMID 36008864, 2022).
tumor (continued). "In cytokine release syndrome (CRS), the tumor cell DNA released by pyroptotic cells during CAR-T therapy is internalized by macrophages, activating the inflammasomes and releasing bioactive IL-1β, IL-18, and other pro-inflammatory cytokines." (PMID 36376979, 2022). "The use of recombinant cytokines is also a way to promote anti-tumor activity, and SB-485232, a recombinant human IL-18 has been used in seven clinicals trials, albeit without showing efficacy." (PMID 35517498, 2022). "We reveal that macrophages in response to chemotherapy secrete interleukin-18, which in turn upregulates expression of L-amino acid transporter 2 (LAT2) in tumor cells for substantially enhanced uptakes of leucine and glutamine, two potent stimulators of mTORC1." (PMID 36274066, 2022). "On the one hand, pyroptosis, a lytic and proinflammatory type of regulated cell death, is characterized by cell swelling, lysis, and the release of numerous proinflammatory factors, including IL-18, ATP, IL-1β, and HMGB1, which can promote tumor growth and progression." (PMID 35784306, 2022). "Therefore, pyroptosis plays an anti-tumor role in the process of tumor formation, while HPV inhibits the progression of pyroptosis by suppressing the expression of IL-1β, IL-18 and inflammasomes, thus promoting tumor progression." (PMID 36497244, 2022). "In this direction, our analysis of the tumor compartment alone shows no prognostic significance for IL9 or IL18 concentrations." (PMID 36131941, 2022). "Increased production of IL-18 and IFN-γ and caspase-1 activation induced by treatment with bLf are important factors contributing to the increase in intestinal mucosal immunity in tumor-bearing mice." (PMID 35264972, 2022). "Inflammatory cytokines that activate host anti-tumor activity include IFN-Γ, IL-12, and IL-18." (PMID 35892729, 2022). "Petrilli and colleagues reported an immunosuppressive role of the Nlrp3-Asc-Caspase-1 pathway, that blunted NK cell tumor recruitment and activation, but that was independent of IL-1β, IL-18 or IL-1 receptor signaling." (PMID 35517498, 2022). "This change in immune profile resulted in successful anti-tumor activity against lung and pancreatic tumours which were refractory against the same treatment without the IL-18." (PMID 35205725, 2022). "Eosinophils, an antitumor immune system independent of T cells, could kill cancer cells directly or suppress the growth of tumor by secreting TNF-α and IL-18." (PMID 36313179, 2022). "While IFN-γ is required for successful tumor destruction, supra-physiological IFN-γ levels may accumulate particularly in case of co-expressed IL18 that can cooperate with IL12 or IL15 to further increase IFN-γ production." (PMID 36700225, 2022). "The description of specific compartmental effects of IL9 and IL18 in the stroma cannot be concluded without looking into the tumor compartment in comparison." (PMID 36131941, 2022). "In this study, we compared the tumor-targeting potential of EVs derived from either primary NK cells or the NK cell lines NK-92 and KHYG-1 cultured in IL-15 alone or in combination with IL-12 and IL-18." (PMID 35119498, 2022). "For example, in GKO mice, while bLF administration did not activate the IFN-γ/caspase-1/IL-18 effector pathway, it inhibited tumor growth and metastasis by activating the IFN-alpha/IL-7 effector pathway." (PMID 35264972, 2022). "IL-18 induced increased expansion of Vδ2 T cells stimulated by ZOL and IL-2, and expanded cells displayed an effector memory phenotype, with high levels of production of IFN-γ, TNF-α and strong cytotoxicity against tumor cells like mesothelioma cells." (PMID 36429001, 2022). "Moreover, systemic expression of IL-12+IL-18 leads to a prevalence of TVM cells expressing IFNγ in tumors and defines these cells as an essential factor for tumor growth control in the early stages of disease." (PMID 36330506, 2022).
tumor (continued). "In order to minimize systemic toxicity and induce the accumulation of high cytokine concentrations at the tumour site, CAR‐T cells were modified to produce IL‐12, IL‐18, IL‐7, IL‐15 and IL‐21 cytokines, and activation and persistence of CAR‐T cells were, therefore, enhanced in vivo." (PMID 34585512, 2021). "M1-type macrophages are critically important in host defense and killing of tumor cells by the production of pro-inflammatory cytokines such as interferon-γ (IFN-γ), TNF-α and IL-18, which have potent microbiome-killing properties and hence are considered as ‘good’ macrophages." (PMID 34646772, 2021). "The use of Il18r1 KO mice or anti-IL-18 treatment did not result in significant differences in tumor growth rate and survival among CTXpre-experienced groups (WT-CTXpre, WT-CTXpre + αIL-18, Il18r1 KO-CTXpre), which had low proportion of IL-18Rαhi T cells." (PMID 34493727, 2021). "Indeed, deletion of HIF1α in NK cells resulted in an improved ability to reduce tumor burden in two independent studies, which was attributed to a dysfunctional VEGF axis or increased effector functions through IL-18 signaling." (PMID 34396954, 2021). "In HCC tumor microenvironment, several cytokines and chemokines such as CXCL1, CSF1, CCL2, CCL9, IL-6, and IL-18 etc., which were secreted from either HCC cells or immune cells, promotes the recruitment and infiltration of MDSCs from the bone marrow into HCC tumor site 32-34." (PMID 33897880, 2021). "In the case of CTXpre-experienced mice, which had lower capacity of generating the IL-18Rαhi subset, inhibition of IL-18 signaling did not significantly change anti-tumor activity." (PMID 34493727, 2021). "In vivo, IL-18 stimulation of human NK cells promoted IFN-γ generation and antibody-dependent cell-mediated cytotoxicity (ADCC) to the lymphoblast-like tumor cell line Raji following treatment with rituximab, making IL-18 a potential cytokine for combination cancer therapy." (PMID 34440725, 2021). "As for M1 macrophages, it could suppress tumor growth by both cytophagocytic effects and the production of TNF-α, reactive oxygen species (ROS), and cytokines like IL-1, IL-12, IL-15, and IL-18 to enhance Th1 response." (PMID 34650926, 2021). "However, IL-18 is also able to enhance IFN-γ production from Th1 cells, leading to natural killer (NK) and CD8+ T cell anti-tumor response." (PMID 33261061, 2020). "With regard to SH-SY5Y, TCR-stimulated γδ T cells showed no significant tumor growth inhibition even at a high E:T ratio of 5:1 except when combined with IL-2/IL-12/IL-18." (PMID 31947966, 2020). "Tumor cell suspensions from WT or Caspase-1 KO mice were incubated with a combination of IL-12+IL-18 cytokines, or with crosslinking antibodies against activating receptors (NKp46, Ly49D, NKG2D) or with different tumor cell lines (4T1, and YAC1 cells, a classical NK cell target)." (PMID 33042810, 2020). "In the absence of a TCR stimulus, only IL-2/IL-12/IL-18- treated γδ T cells exerted a clear and lasting anti-tumor effect, even at a low E:T ratio, i.e., of 0.5:1." (PMID 31947966, 2020). "Purified ILCs from non-affected colon, tumor border and central tumor tissue were cultured in the presence of IL-2 plus IL-1β and IL-18 for 7−9 days and the resulting expression of HLA-DR and T-cell co-stimulatory molecules was assessed." (PMID 32341343, 2020). "Furthermore, combined gene therapy with interleukin 18 (IL-18) gene and HSV1-tk under hTERT promoter transcriptional control has been carried out, this strategy confers a specific anti-tumor immunity, partially or completely eliminating tumors." (PMID 33381459, 2020).